PGRMC1 (progesterone receptor membrane component 1)
Diseases named in the same sentence as PGRMC1 in open-access papers (continued):
Sharing a sentence is not in itself a finding about the gene and the disease.
tumor (continued). "In the present study, we observed that the knockdown of Pgrmc1 led to decreased inflammatory responses in macrophages accompanied by downregulation of EGFR, indicating the tumor-promoting role of Pgrmc1 in macrophages." (PMID 34069911, 2021). "Because PGRMC1 plays a role in chemoresistance, tumor progression and growth it has become an attractive therapeutic target." (PMID 34350123, 2021). "In MCF-7 and MDA-MB-231 tumor cell lines, the migratory activity was evaluated after Pgrmc1 knockdown." (PMID 33832499, 2021). "In backcrossed FVB Pgrmc1 knockout (KO) mice, we monitored the development of the primary tumor and lung metastasis." (PMID 33832499, 2021). "In the present study, Pgrmc1 KO mice showed a slight decrease in tumor development along with a decrease in the expression of PR." (PMID 33832499, 2021). "Our findings suggest the function of PGRMC1 as an important enhancer especially of lipid synthesis resulting in oncogenic signaling and tumor progression." (PMID 32660617, 2020). "In a methylomics study of these cells in the companion paper, the most significantly down-regulated KEGG pathway in the TM/DM comparison was PI3K-AKT, consistent with PI3K/AKT activation requiring PGRMC1 Y180, which was required for tumor growth." (PMID 32245408, 2020). "In normal tissues, PGRMC1 increases lipid synthesis by binding and activating P450 proteins, while in tumour cells, PGRMC1 deeply affects cell signalling." (PMID 32672400, 2020). "As already shown in previous studies by us and others, PGRMC1 overexpression results in increased proliferation of tumor cells." (PMID 32660617, 2020). "To further strengthen our theory, we examined the impact of PGRMC1 silencing on tumor proliferation by knocking down endogenous PGRMC1 expression." (PMID 32660617, 2020). "Heme-dependent dimerization of PGRMC1 has been shown to accelerate tumor growth through the EGFR signaling pathway and facilitate cancer proliferation and chemoresistance." (PMID 32179851, 2020). "We studied PGRMC1 expression in human tumour tissue by comparing the genotype-tissue expression (GTEx) portal data pertaining to normal breast tissue and The Cancer Genome Atlas (TCGA)." (PMID 32704174, 2020). "PGRMC1 promotes various phenotypes in the tumorigenesis, including tumor growth, invasion, metastasis, and apoptotic resistance." (PMID 31970154, 2019). "In contrast, the tumor samples harboring PGRMC1 high-expression have reduced the genomic alterations rate of NOTCH1 genes." (PMID 31970154, 2019). "Since PGRMC1 is aberrantly up-regulated expressed in tumor samples, we next investigated the clinical implication of PGRMC1 expression in HNSC patients." (PMID 31970154, 2019). "In summary, these data demonstrate a strong positive correlation between PGRMC1 expression and tumor metabolism activity, a key step in oncogenesis." (PMID 31970154, 2019). "And the elevated PGRMC1 level was related to the tumor malignancy degree and overall survival of RCC patients." (PMID 28107520, 2017). "In summary, the up-regulated PGRMC1 is statistically correlated with the tumor malignancy degree of RCC TNM stages." (PMID 28107520, 2017). "In summary, the present findings implicate elevated PGRMC1 expression in a broad range of tumor types." (PMID 27867772, 2015). "Stem cells were isolated from surgical specimens at Marshall University using a PBRX bioreactor, and western blots revealed abundant PGRMC1 in isolated stem cells as well as in the bulk of the tumor." (PMID 27867772, 2015). "PGRMC1 was expressed in two different patient-derived tumor stem cell populations and was required for viability in those cells." (PMID 27867772, 2015). "We demonstrate here that PGRMC1 is elevated in multiple tumor types, including head and neck cancer and in oral cancer." (PMID 27867772, 2015). "Previous reports in tumor cells indicate that PGRMC1 protein is localized to intracellular compartments and the plasma membrane." (PMID 25390692, 2014).
tumor (continued). "The PGRMC1 had been reported to be more abundant in several tumours and/or tumour cell lines than in healthy control tissues including the lung, breast, colon and thyroid cancer cell lines." (PMID 24330526, 2013). "A possibility exists in that the newly discovered progesterone receptor membrane component 1 (PGRMC1) or the family of membrane PRs (mPRα, β, γ, δ, ε) mediate the anti-tumor effects of MF." (PMID 21619605, 2011). "The protein encoded by this gene belongs to the same family as Hpr6 (also called PGRMC1) which was found to increase the resistance of tumor cells to DNA-damaging agents." (PMID 19851466, 2009). "Differentially detected spots of Progesterone Receptor Membrane Component 1 (PGRMC1) were shown to differ in phosphorylation status by differential two dimensional polyacrylamide gel electrophoresis of phosphatase-treated tumor proteins." (PMID 18922159, 2008). "In ductal in situ breast cancers of comedo-type, PGRMC1 was present in cells surrounding the necrotic centre of the tumor, whereas ER-α was expressed in cells more distal to the necrotic centre." (PMID 18922159, 2008). "Further studies in a larger patient collective will be necessary to correlate specific PGRMC1 isoforms with other tumor markers in addition to ER-α." (PMID 18922159, 2008). "We detected an expected wound response signature in ER-α-neg tumors that was associated for the first time with differential abundance, and phosphorylation of PGRMC1 between different tumor types." (PMID 18922159, 2008). "Additionally, research on the upstream and downstream regulatory factors of PGRMC1 in tumor cells remains limited, and its specific signal transduction network in hormone replacement therapy has not been fully elucidated." (PMID 41153737, 2025). "Designing drugs that specifically target PGRMC1 could inhibit tumor cell survival and proliferation." (PMID 41153737, 2025). "Accumulating evidence links PGRMC1 to carcinogenesis and tumour progression." (PMID 37887342, 2023). "In conclusion, PGRMC1 enhances tumour-related inflammation and promotes the progression of GBM." (PMID 37887342, 2023). "Interestingly, our analysis revealed significant alterations in the expression of CCM2, CCM3, PGRMC1, and nPRs across various tumor-staging categories." (PMID 35971177, 2022). "Although the reduction of MMP2 was marginal, the reductions in FAK, mesenchymal markers, and MMP9 in Pgrmc1 KO mice may be considered as comprising a challenging environment for the migration of tumor cells." (PMID 33832499, 2021). "Inhibition of PGRMC1 by GL derivatives may be involved in reducing the amount of LDL uptake into cells to suppress tumor growth." (PMID 34209885, 2021). "Likewise, Pgrmc1 KO mice had a significantly smaller metastatic tumor area (p < 0.05, 19.6% compared with WT mice)." (PMID 33832499, 2021). "Importantly, in the long-term in vivo study (>100 weeks), the ablation of Pgrmc1 led to a notable extension of the survival duration in HCC-bearing mice by suppressing the tumor development." (PMID 34069911, 2021). "Interestingly, the PGRMC1 mRNA expression is also positive correlated with tumor stemness in RNA level score." (PMID 34746100, 2021). "In this light, dioxin-induced expression of PGRMC1 could account for much of dioxin’s ability to promote tumor development, since PGRMC1 functions to promote cell survival as will be discussed later in this review." (PMID 34885064, 2021). "Besides, PGRMC1 expression correlates with metastasis to lymph nodes, larger tumor size, and poorer overall- and tumor-free survival." (PMID 32660617, 2020). "Nevertheless, little is known about the mechanisms by which PGRMC1 drives tumor progression." (PMID 32660617, 2020).
tumor (continued). "One consequence could be that PGRMC1 promotes tumor progression by upregulation of ERα protein and ESR1 mRNA directly via a transcriptional mechanism or indirectly via elevated steroid synthesis." (PMID 32660617, 2020). "Our results point towards an upregulation of lipid synthesis due to PGRMC1 overexpression in hormone receptor-positive breast cancer, which might lead to enhanced tumor growth." (PMID 32660617, 2020). "Our data suggest that, in MF and P4 action, PGRMC1 may be the key LCT P4 receptor in the tumor-promoting action of TGFβ1." (PMID 33158280, 2020). "In conclusion, based on our results, we suggest that MF in low concentration may act as a membrane PR agonist and activate through PGRMC1 the tumor progression signaling pathway of TGFβ1 superfamily in LCTs." (PMID 33158280, 2020). "More recently, sigma-2/PGRMC1 has been described as a possible drug target in cancer where it is overexpressed in tumor cells, but it has not been previously associated with AD." (PMID 25390692, 2014). "There are therefore a variety of theoretically possible mechanisms whereby differential PGRMC1 abundance and phosphorylation could affect tumor biology, perhaps with a central nexus functionality." (PMID 18922159, 2008). "However, the effect was stronger in tumour cells with high PGRMC1 expression." (PMID 39464509, 2024). "Our study identifies PGRMC1 as a tumour-promoting factor and modulator of the tumour microenvironment that may serve as an independent prognostic marker for the overall survival of GBM patients and, most importantly, as a target for novel therapeutic strategies in GBM." (PMID 37887342, 2023). "We also assessed the expression level of glypican-3 (GPC3), a biomarker for diagnosis and prognosis of HCC, to address whether Pgrmc1 modulates HCC malignancy in vivo, and found that the GPC3 expression level in the tumor regions was comparable between WT and Pgrmc1-null livers." (PMID 34069911, 2021). "Therefore, the discovery of compounds targeting heme-dimerized PGRMC1 could lead to the development of novel drugs targeting various PGRMC1 functions, including its effect on tumor progression." (PMID 34209885, 2021). "However, unlike PAQR5, PGR and PGRMC1 downregulation were not consistently associated with tumor progression in TNM categories, lymph node invasion, and distal metastasis." (PMID 34572596, 2021). "Progesterone Receptor Membrane Component 1 (PGRMC1/Sigma-2 receptor) is located on chromosome Xq21 and encodes a haem-containing protein that interacts with epidermal growth factor receptor (EGFR) and cytochromes P450, with function in tumor proliferation and chemoresistance." (PMID 31970154, 2019). "There are a number of potential mechanisms through which PGRMC1 might promote tumor growth." (PMID 27867772, 2015). "The results of our studies show that disruption of PGRMC1 signalling by AG-205 reduced cell viability in tumour (COV434) and non-tumour (HGrC1) cell lines." (PMID 39464509, 2024). "To illuminate the difference observed between the two tumor cell lines, we performed Western blot experiments of whole cell lysates to evaluate the expression levels of TMEM97 and PGRMC1." (PMID 37047353, 2023). "Specifically, PGRMC1 dimerizes in a heme-dependent manner and subsequently binds to EGFR, thereby enhancing tumour aggressiveness." (PMID 37887342, 2023). "PGRMC1 expression elevated FAO and ferroptosis sensitivity from in vivo mice experiments with tumor transplantation." (PMID 34749765, 2021).
tumor (continued). "Similarly, Asperger and co-workers found that downregulation of endogenous PGRMC1 decreased the viability of MCF7 and T47D cells, while PGRMC1 overexpression led to formation of larger tumours in murine xenograft models." (PMID 37887342, 2023). "Taken together, these data indicate that PGRMC1 may be a therapeutic target in GBM and that patients with high tumour expression of PGRMC1 might benefit from individualized therapeutic approaches with ferroptosis inducers." (PMID 37887342, 2023). "Progesterone receptor membrane component 1 (PGRMC1), a non-classical membrane progesterone receptor, has been associated with the progression of HCC from tumor size G2 to G3 and has been explored as a possible prognostic biomarker for HCCs." (PMID 36980321, 2023). "PGRMC1 is overexpressed in tumour tissues compared to non-malignant control tissues in multiple solid cancers." (PMID 37887342, 2023). "Interestingly, we observed significant differential expression in HCC patients for CCM2, PGRMC1, and nPRs, along with AFP, demonstrating the importance of the CmPn network in influencing tumor recurrence." (PMID 36980321, 2023). "Tumor weight per body weight was lower in Pgrmc1 KO mice, albeit the difference was not statistically significant (p = 0.2544)." (PMID 33832499, 2021). "Interaction between PGRMC1 and EGFR has been shown to promote tumor growth." (PMID 32867363, 2020). "Our findings collectively demonstrate that Pgrmc1 plays a tumor-promoting function in non-parenchymal cells through the modulation of EGFR expression and may serve as a potential target for treating HCC." (PMID 34069911, 2021). "After stably knockdown cell line establishment, we performed immunoblotting to validate the PGRMC1 expression levels in OC3 and OC3‐I5 cells transfected with shPGRMC1 or shLacZ, and the invasion ability of cells was also investigated before tumour implantation in mice." (PMID 32672400, 2020). "Anatomical tumor recurrence between the lungs, liver, lymph nodes, bones, and brain revealed significant differential expression for CCM1, PAQR9, and PGRMC1, along with AFP, in HCC patients, while no significance was observed for CCA patients." (PMID 36980321, 2023).
neurodegenerative disease (3 papers, 2014 to 2024). A disorder of the central nervous system characterized by gradual and progressive loss of neural tissue and neurologic function. "We found that the reduction in PGRMC1 levels activated the NF-κB and ER stress pathways, leading to an increase in indicators that are associated with neurodegenerative diseases due to pro-inflammatory cytokine elevation." (PMID 38397828, 2024). "This evidence presents PGRMC1 as one of the genes that can potentially treat neurodegenerative diseases." (PMID 38397828, 2024). "Our findings provide important new information about actions of Pgrmc1 in neural cells, and suggest new areas for exploration in the search for therapeutic targets to better treat neurodegenerative diseases." (PMID 31026287, 2019). "Therefore, the decrease in PGRMC1 is revealed to facilitate neurodegenerative diseases, which was attributed to the increased inflammatory response." (PMID 38397828, 2024). "To date, there are no reports of mutations in sigma-2/PGRMC1 that are associated with neurodegenerative diseases, human but mutations in this receptor are very rare, suggesting this gene is essential." (PMID 25390692, 2014).
head and neck tumors (1 paper, 2015). "PGRMC1 was significantly elevated in all head and neck tumors (n = 173) compared to corresponding normal tissues (n = 23, p = 0.004, 2-sided t-test)." (PMID 27867772, 2015).
infection (1 paper, 2021). The state of being infected such as from the introduction of a foreign agent such as serum, vaccine, antigenic substance or organism. "Toward this aim, we assessed RIG-I ubiquitination in PGRMC1-KO U251 cells or wild-type (WT) U251 cells transfected with the pCAGGS-HA-Ub vector or the empty vector along with or without p3×Flag-RIG-I, followed by infection with JX." (PMID 34585989, 2021).
metabolic disorders (1 paper, 2025). "Targeting PGRMC1 may confer muscle‐specific metabolic benefits, with possible implications beyond T2D to other muscle‐related metabolic disorders." (PMID 41208560, 2025).
PGRMC1 also shares sentences with these, for which no sentence is quoted: pancreatic cancer (3 papers); esophageal cancer (2); Hyperglycemia (2); leukemia (2); lung squamous cell carcinoma (2); neurological disease (2); uterine sarcoma (2); acute myelocytic leukemia (1); adenocarcinoma (1); alcoholism (1); breast ductal carcinoma (1); cervical intraepithelial neoplasia (1); deficient (1); depression (1); Energy (1); gastric cancer (1); hepatic angiosarcoma (1); hyperinsulinism (1); inflammation (1); injury (1); ischemic stroke (1); large cell lung cancer (1); Leydig cell tumor (1); liver inflammation (1); melanoma (1); non-alcoholic fatty liver disease (1); pancreatic adenocarcinoma (1); psychiatric disorder (1); sarcoma (1); serous ovarian tumors (1).
A further 4 diseases each share a sentence with PGRMC1 in 1 paper.